UNC93B7 (unc-93 homolog B7 (pseudogene))
Gene: Transcribed unprocessed pseudogene on chromosome 4 (9,493,736 to 9,498,066, forward strand). Ensembl gene ENSG00000251624.
Diseases named in the same sentence as UNC93B7 in open-access papers:
UNC93B7 is named in the same sentence as 1 disease in open-access papers, as found by Europe PMC text mining. Sharing a sentence is not in itself a finding about the gene and the disease. The quoted sentences say what the papers report.
glioblastoma (1 paper, 2023). The most malignant astrocytic tumor (WHO grade IV). "Two genes, AC017104.4 and UNC93B7, were found to be specific for patients with IDH1-wt, TERT-promoter-mutated, and MGMT-methylated glioblastoma." (PMID 37568598, 2023).